BTK (Bruton tyrosine kinase)
Description:
Non-receptor tyrosine kinase indispensable for B lymphocyte development, differentiation and signaling. Binding of antigen to the B-cell antigen receptor (BCR) triggers signaling that ultimately leads to B-cell activation. After BCR engagement and activation at the plasma membrane, phosphorylates PLCG2 at several sites, igniting the downstream signaling pathway through calcium mobilization, followed by activation of the protein kinase C (PKC) family members. PLCG2 phosphorylation is performed in close cooperation with the adapter protein B-cell linker protein BLNK. BTK acts as a platform to bring together a diverse array of signaling proteins and is implicated in cytokine receptor signaling pathways. Plays an important role in the function of immune cells of innate as well as adaptive immunity, as a component of the Toll-like receptors (TLR) pathway. The TLR pathway acts as a primary surveillance system for the detection of pathogens and are crucial to the activation of host defense. Especially, is a critical molecule in regulating TLR9 activation in splenic B-cells. Within the TLR pathway, induces tyrosine phosphorylation of TIRAP which leads to TIRAP degradation. BTK also plays a critical role in transcription regulation. Induces the activity of NF-kappa-B, which is involved in regulating the expression of hundreds of genes. BTK is involved on the signaling pathway linking TLR8 and TLR9 to NF-kappa-B. Acts as an activator of NLRP3 inflammasome assembly by mediating phosphorylation of NLRP3. Transiently phosphorylates transcription factor GTF2I on tyrosine residues in response to BCR. GTF2I then translocates to the nucleus to bind regulatory enhancer elements to modulate gene expression. ARID3A and NFAT are other transcriptional target of BTK. BTK is required for the formation of functional ARID3A DNA-binding complexes. There is however no evidence that BTK itself binds directly to DNA. BTK has a dual role in the regulation of apoptosis. Plays a role in STING1-mediated induction of type I interferon (IFN) response by phosphorylating DDX41.
Synonyms: ATK; BPK; AGMX1; XLA; PSCTK1; AT; IGHD3; IMD1
Tractability: Small molecule: an approved drug acts on it; a structure with a bound ligand is known; a high-quality ligand is known; it has a high-quality binding pocket; it belongs to a druggable protein family. Antibody: UniProt places it where antibodies can reach, with high confidence; its Gene Ontology location is reachable by antibodies, with high confidence; the Human Protein Atlas places it where antibodies can reach. PROTAC: a drug acting on it is in phase 1 trials; it is named in the literature on targeted protein degradation; ubiquitination databases record sites on it; its protein half-life has been measured; a small molecule that binds it is known.
Target class: TK protein kinase group; Kinase; Protein Kinase; Enzyme; Tyrosine protein kinase Tec family
Chemical probes: CGI1746 (high quality), DD-03-171 (high quality), DGY-06-116 (high quality), GDC-0834 (high quality), IBRUTINIB, IR-2 (high quality), PD134261, PD134262, PD134263, PD134264, PD134266, PD134267, PD134269, PD134271, PD134273, PD134275, PD134277, SPEBRUTINIB (high quality), rilzabrutinib
Gene: Protein-coding gene on chromosome X (101,349,338 to 101,390,796, reverse strand). Ensembl gene ENSG00000010671.
Subcellular location: Cytoplasm; Cell membrane; Nucleus; Membrane raft
Subcellular location (Human Protein Atlas): Cytosol; Plasma membrane
Pathways (Reactome):
Immune System: Antigen activates B Cell Receptor (BCR) leading to generation of second messengers; DAP12 signaling; ER-Phagosome pathway; FCERI mediated Ca+2 mobilization; MyD88:MAL(TIRAP) cascade initiated on plasma membrane; Regulation of actin dynamics for phagocytic cup formation
Disease: FCGR3A-mediated phagocytosis; IRAK4 deficiency (TLR2/4); MyD88 deficiency (TLR2/4); Potential therapeutics for SARS
Signal Transduction: G alpha (12/13) signalling events; G alpha (q) signalling events; G beta:gamma signalling through BTK; RHO GTPases Activate WASPs and WAVEs
Gene Ontology:
Molecular function: identical protein binding; non-membrane spanning protein tyrosine kinase activity; phosphatidylinositol-3,4,5-trisphosphate binding; phospholipase activator activity; phospholipase binding; protein binding; protein tyrosine kinase activity; ATP binding; protein kinase activity
Biological process: B cell receptor signaling pathway; intracellular signal transduction; peptidyl-tyrosine phosphorylation; positive regulation of cGAS/STING signaling pathway; positive regulation of NLRP3 inflammasome complex assembly; adaptive immune response; apoptotic signaling pathway; B cell activation; calcium-mediated signaling; Fc-epsilon receptor signaling pathway; innate immune response; mesoderm development; MyD88-dependent toll-like receptor signaling pathway; positive regulation of B cell differentiation; positive regulation of canonical NF-kappaB signal transduction; regulation of B cell apoptotic process; regulation of B cell cytokine production; T cell receptor signaling pathway; cellular response to molecule of fungal origin; cellular response to reactive oxygen species; eosinophil homeostasis; histamine secretion by mast cell; monocyte proliferation; negative regulation of B cell activation; negative regulation of cytokine production; and 15 more
Cellular component: cytoplasm; cytosol; membrane raft; nucleus; plasma membrane; cytoplasmic vesicle; perinuclear region of cytoplasm
Gene-disease validity (ClinGen):
ClinGen rates the evidence that BTK causes each of these diseases.
Bruton-type agammaglobulinemia (X-linked): Definitive. X-linked agammaglobulinemia (XLA) is a clinically variable form of isolated agammaglobulinemia, an inherited immunodeficiency disorder, and is characterized in affected males by recurrent bacterial infections during infancy.
isolated growth hormone deficiency type III (X-linked): Disputed.
Cancer hallmarks: escaping programmed cell death (promotes); genome instability and mutations (promotes); escaping programmed cell death (suppresses); cell replicative immortality (promotes)
Homologues: Orthologues: chimpanzee BTK (100% identical), macaque BTK (100% identical), pig BTK (99% identical), dog BTK (99% identical), rabbit BTK (99% identical), guinea pig BTK (99% identical), rat Btk (98% identical), mouse Btk (98% identical), tropical clawed frog btk (73% identical), zebrafish btk (63% identical). Paralogues in human: TEC (53% identical), BMX (50% identical), ITK (49% identical), TXK (42% identical), ABL2 (29% identical), ABL1 (29% identical), FRK (28% identical), FYN (27% identical), LYN (27% identical), SRC (27% identical), YES1 (27% identical), BLK (26% identical), and 20 more.
Diseases named in the same sentence as BTK in open-access papers:
BTK is named in the same sentence as 357 diseases in open-access papers, as found by Europe PMC text mining. Sharing a sentence is not in itself a finding about the gene and the disease. The quoted sentences say what the papers report.
chronic lymphocytic leukemia (299 papers, 2014 to 2026). "Mutations or increased expression of BTK are correlated in many types of B cell-derived malignancy, including chronic lymphocytic leukemia (CLL) and other B cell cancers." (PMID 39925800, 2025). "Ibrutinib (Bruton's tyrosine kinase (BTK) inhibitor nowadays used for refractory chronic lymphocytic leukemia or mantle cell lymphoma increases the risk of atrial fibrillation potentially via inhibition of cardiac PI3K-Akt signaling." (PMID 37711551, 2023). "BTK has been reported to be associated with a variety of severe human diseases, including chronic lymphocytic leukemia and certain hyperactivated inflammatory responses after infection." (PMID 37630287, 2023). "Chronic lymphocytic leukemia patients have an increased bleeding risk with the introduction of Bruton tyrosine kinase (BTK) inhibitors." (PMID 36497231, 2022). "Bcr-Abl is a tyrosine kinase that is known to play a major role in chronic myelogenous leukemia (CML), while Bruton’s tyrosine kinase (BTK) is implicated in B-cell malignancies (chronic lymphocytic leukemia and non-Hodgkin lymphomas)." (PMID 34299488, 2021). "Acquired mutations at this locus, which often arise as a result of BTK inhibition to treat chronic lymphocytic leukemia, result in constitutive downstream signaling and lymphocyte proliferation." (PMID 34157287, 2021). "Ibrutinib, an oral inhibitor of the Bruton’s tyrosine kinase (BTK) has proved to be remarkably efficient against treatment naïve (TN), heavily pre-treated and high-risk chronic lymphocytic leukaemia (CLL), with limited adverse events." (PMID 31076570, 2019). "Ibrutinib resistance is mostly due to specific mutation of BTK or phospholipase gamma downstream of BTK, and these mutations frequently lead to a Richter transformation from chronic lymphocytic leukemia to diffuse large B cell lymphoma." (PMID 30460325, 2018). "Patients with chronic lymphocytic leukemia (CLL) that develop resistance to Bruton tyrosine kinase (BTK) inhibitors are typically positive for mutations in BTK or phospholipase c gamma 2 (PLCγ2)." (PMID 28212557, 2017). "Infection susceptibility varies across BTK inhibitor generations, reflecting differences in kinase selectivity, modulation of humoral and cellular immunity, and disease-intrinsic immune dysfunction in chronic lymphocytic leukemia." (PMID 42192981, 2026). "Background/Objectives: Covalent Bruton’s tyrosine kinase (BTK) inhibitors (ibrutinib, acalabrutinib, zanubrutinib) improve outcomes in advanced chronic lymphocytic leukemia (CLL) but resistance, largely driven by BTK C481 mutations, and adverse events limit long-term benefit." (PMID 41008818, 2025). "On the other hand, constitutive activation of BTK is often linked to several forms of B-cell leukemias and lymphomas like chronic lymphocytic leukemia, and diffuse large B cell lymphoma (ABC-DLBCL), suggesting a critical regulatory function of BTK in B-cell development and proliferation." (PMID 38971313, 2024). "For instance, in chronic lymphocytic leukemia, hypermorphic PLCγ2 mutations are associated with resistance to Bruton’s tyrosine kinase (BTK) inhibition by ibrutinib, which provokes constitutive downstream signaling (e.g., IP3 production and Ca2+ release) and B cell proliferation." (PMID 38811530, 2024).
chronic lymphocytic leukemia (continued). "Ibrutinib, the first representative of BTK inhibitors, significantly improved the prognosis in high genetic risk chronic lymphocytic leukemia (CLL) resistant to traditional chemoimmunotherapy, in mantle cell lymphoma and in Waldenström’s macroglobulinemia as well." (PMID 33567947, 2021). "In particular, the orally administered irreversible BTK inhibitor ibrutinib is associated with high response rates in patients with relapsed/refractory chronic lymphocytic leukemia (CLL) and mantle-cell lymphoma (MCL), including patients with high-risk genetic lesions." (PMID 29455639, 2018). "Ibrutinib, a Bruton tyrosine kinase inhibitor, is widely used in chronic lymphocytic leukemia (CLL)." (PMID 41559979, 2026). "Ibrutinib is a Bruton's tyrosine kinase (BTK) inhibitor widely used in the treatment of B-cell malignancies, including chronic lymphocytic leukemia (CLL)." (PMID 41684975, 2026). "Bruton’s Tyrosine Kinase (BTK) is an anchor in B-cell receptor signaling and plays an important role in chronic lymphocytic leukemia (CLL)." (PMID 41266486, 2025). "Whilst covalent Bruton’s tyrosine kinase (BTK) inhibitor therapy improves outcomes in chronic lymphocytic leukemia (CLL), resistance and adverse effects limit their long-term use." (PMID 41008818, 2025). "Acalabrutinib is a highly selective Bruton tyrosine kinase inhibitor approved in the United States and Europe for chronic lymphocytic leukemia (CLL) based on phase 3 trials with limited representation of Asian populations." (PMID 39271521, 2025). "Currently, the PROTAC drug Vepdegestrant, which targets estrogen receptors in breast cancer, has completed phase III clinical trials, and PROTAC drugs such as BGB-16673, which target BTK in chronic lymphocytic leukemia, have entered phase III clinical trials." (PMID 41244073, 2025). "In contrast to chronic lymphocytic leukemia (CLL) and Waldenström macroglobulinemia (WM), where BTK C481 mutations are common and represent the dominant cause of resistance, such mutations are rare in MCL." (PMID 40944468, 2025). "First-generation Bruton’s tyrosine kinase (BTK) inhibitor ibrutinib was the first of this class of drugs introduced as a central therapeutic agent for chronic lymphocytic leukemia (CLL), ushering in the era of kinase-targeting medications for this disease." (PMID 40453665, 2025). "Bruton tyrosine kinase inhibitors (BTKis) are effective and well-tolerated treatments for chronic lymphocytic leukemia (CLL) and mantle cell lymphoma (MCL)." (PMID 40815495, 2025). "BTK inhibitors are approved in many hematologic malignancies: chronic lymphocytic leukaemia, mantle cell lymphoma, marginal zone lymphoma, Waldenström macroglobulinaemia and follicular lymphoma." (PMID 39887627, 2025). "In another study investigating COVID-19 vaccine antibody responses in patients with chronic lymphocytic leukemia, individuals receiving BTK inhibitors showed markedly reduced humoral and cellular immune responses." (PMID 40733703, 2025). "More than half of infection-related deaths were caused by other agents, serving as a reminder of the immunosuppressive effect of chronic lymphocytic leukemia (and, to a lesser degree, Bruton tyrosine kinase inhibition)." (PMID 40723186, 2025). "Future investigations should aim at identifying predictive factors, mechanisms, and preventive strategies for reducing cardiotoxicity in chronic lymphocytic leukemia patients taking Bruton tyrosine kinase inhibitors." (PMID 40723186, 2025). "Bruton's tyrosine kinase (BTK) inhibitors have been shown to be a promising treatment option for patients with chronic lymphocytic leukemia (CLL)." (PMID 40351903, 2025).
chronic lymphocytic leukemia (continued). "The first-generation BTK inhibitor, ibrutinib, rapidly became the standard of care for treating patients with certain subtypes of non-Hodgkin lymphoma and chronic lymphocytic leukemia (CLL)." (PMID 40145086, 2025). "Since its discovery, the BTK inhibitor ibrutinib has redefined the standard treatments for hematological cancers, such as chronic lymphocytic leukemia (CLL)." (PMID 40940754, 2025). "Ibrutinib, a TKI with high affinity for Bruton tyrosine kinase, is used in the treatment of chronic lymphocyte leukemia and has been shown to also inhibit HER4 and other TKs." (PMID 41007372, 2025). "Ibrutinib and acalabrutinib are first- and next-generation Bruton Tyrosine Kinase inhibitors (BTKi), respectively, approved for chronic lymphocytic leukemia (CLL)." (PMID 40744952, 2025). "Different BTK inhibitors such as ibrutinib and acalabrutinib are approved for the treatment of certain B-cell malignancies (e.g., chronic lymphocytic leukemia)." (PMID 40676697, 2025). "The introduction of the covalent Bruton’s tyrosine kinase (BTK) inhibitors ibrutinib, acalabrutinib, and zanubrutinib has revolutionized the treatment paradigm and improved outcomes for patients with advanced chronic lymphocytic leukemia (CLL)." (PMID 41008818, 2025). "As a critical protein in BCR signal transduction, BTK is an attractive drug target for B-cell malignancies (such as chronic lymphocytic leukemia and mantle cell lymphoma) and autoimmune and inflammatory disorders." (PMID 40453665, 2025). "The MCL (Mantle cell lymphoma) and CLL (chronic lymphocytic leukemia) have both been treated with the BTK inhibitors, by inhibiting BCR signaling and controlling innate or adaptive immunity." (PMID 39898116, 2025). "Based on the crucial role of BTK, abnormalities in BTK can lead to chronic lymphocytic leukemia (CLL)/small lymphocytic lymphoma, mantle cell lymphoma (MCL), Waldenström’s macroglobulinemia, and so on." (PMID 41376625, 2025). "Considering its claimed potency and selectivity toward BTK, TL-895 is a promising therapeutic option for chronic lymphocytic leukemia with the potential to improve safety over existing BTK inhibitors and induce more on-target, durable responses." (PMID 40844833, 2025). "It is followed by Bavdegalutamide, which aims to degrade the androgen receptor in metastatic prostate cancer, and NX-5948, which targets BTK, a key driver in chronic lymphocytic leukemia." (PMID 41515330, 2025). "Activation of the BTK signalling pathway results in malignant B-cell proliferation and activation, contributing to the development of chronic lymphocytic leukaemia (CLL), MCL, diffuse large B-cell lymphoma (DLBCL), or follicular lymphoma (FL)." (PMID 40793752, 2025). "Ibrutinib, the first-generation BTK inhibitor, was approved for treating B cell malignancies including chronic lymphocytic leukemia, small lymphocytic lymphoma, mantle cell lymphoma, marginal zone lymphoma, and Waldenstrom macroglobulinema." (PMID 40345950, 2025). "Inhibitors of Bruton's tyrosine kinase (BTK) in chronic lymphocytic leukemia (CLL) result in durable responses in nearly all patients." (PMID 39157626, 2024). "The development and approval of ibrutinib, the first Bruton’s tyrosine kinase (BTK) inhibitor, revolutionized management of B-cell malignancies like chronic lymphocytic leukemia (CLL)." (PMID 38829647, 2024). "Inhibition of Bruton’s tyrosine kinase (BTK) has proven to be highly effective in the treatment of B-cell malignancies such as chronic lymphocytic leukemia (CLL), autoimmune disorders, and multiple sclerosis." (PMID 39728925, 2024). "Bruton’s Tyrosine Kinase (BTK) inhibitors have become one of the most vital drugs in the therapy of chronic lymphocytic leukemia (CLL)." (PMID 38791284, 2024).